IFNG (interferon gamma)
Diseases named in the same sentence as IFNG in open-access papers (continued):
Sharing a sentence is not in itself a finding about the gene and the disease.
malaria (continued). "On ICS, IFNγ production by CS-specific CD4+ T cells was associated with a reduced risk of clinical malaria of borderline significance (p = 0.07)." (PMID 21998698, 2011). "In vitro parasite-specific IFNγ responses have been shown by us and others to associate with protection against malaria both amongst volunteers undergoing experimentally induced infection and naturally-exposed human populations." (PMID 22144890, 2011). "These receptors initiate signalling cascades that activate nuclear factor kappa B (NF‐κB), leading to increased production of pro‐inflammatory cytokines such as TNF‐α, interferon‐gamma (IFN‐γ), IL‐1β and IL‐6, all of which are implicated in the pathogenesis of malaria." (PMID 40847608, 2025). "However, the translational potential of TNFα and LTα for human CM is questionable, as, similar to IFNγ, TNFα and its receptors are associated with gaining immunity against malaria." (PMID 35514965, 2022). "Ex vivo, Vγ9Vδ2 T-cell proliferation, TNFα, and IFNγ production and immune-modulatory gene expression was also negatively associated with prior malaria episodes—indicating decreased peripheral blood Vγ9Vδ2 T-cell activity with increasing exposure to the parasite." (PMID 30538708, 2018). "Indeed, IFNγ can directly cause apoptosis of erythroid progenitors in vitro and it has been previously implicated in malarial anaemia in rodent malaria models." (PMID 28938907, 2017). "We identified an important transcriptional regulator called B lymphocyte-induced maturation protein 1 (Blimp-1), which promotes IL-10 production by IFNγ-producing CD4+ T (Tr1) cells during malaria and visceral leishmaniasis, two important diseases caused by protozoan parasites." (PMID 26765224, 2016). "The main polymorphism in the gene encoding IFN-γ (IFNG + 874 T/A polymorphism) is located in its first intron at position +874 and studies have reported only weak associations between IFNG SNPs and susceptibility to severe malaria." (PMID 25627396, 2015). "However, when assessed in a multivariate model, the frequency of malaria-specific IFNγ/IL-10 co-producing CD4+ T cells remained strongly associated with the duration since malaria, whereas the total prior incidence was no longer significant." (PMID 24415936, 2014). "We hypothesized that CD4+ T cells producing the pro-inflammatory cytokines IFNγ and/or TNFα are associated with protection from malaria, and that T cell production of the regulatory cytokine IL-10 may interfere with the acquisition of protection." (PMID 24415936, 2014). "To investigate a potential role for UA in malaria pathogenesis, we first measured the levels of ten cytokines (IL-6, IL-10, MCP-1, sTNFRII, IL-8, IP-10, TNFα, IFNγ, GM-CSF and IL-1β) that other studies have implicated in the development of severe malaria in humans." (PMID 23071567, 2012). "IFNγ has been associated with both the pathogenesis and protection against human malaria." (PMID 23323093, 2012). "Phenotypic characterization of the in vitro IFNγ response to whole blood-stage parasites (PfRBC) in malaria-naive donors has variously implicated ‘innate’ natural killer (NK) cells, ‘semi-innate’ γδT cells (including NK-like γδT cells) and ‘adaptive’ αβT cells." (PMID 22144890, 2011). "This could also include vaccine delivery systems and adjuvants, e.g. AS01, currently under investigation in malaria and herpes zoster vaccine candidates, caused NK cell activation in lymph nodes with resulting IFNγ production that was important for DC activation and Th1-induced vaccine response." (PMID 34584101, 2021). "Years of studies on malaria have shown a critical role for proinflammatory cytokines in pathogenesis of the disease and high levels of proinflammatory cytokines such as TNFα, IL-6 and IFNγ have long been linked to acute phases of malaria, including cerebral malaria." (PMID 29495555, 2018).
malaria (continued). "Since IFNγ plays an important role in protective immunity to P. falciparum infection, it is plausible that expression of an anti-inflammatory cytokine milieu during helminth infection might exacerbate malaria pathogenesis and susceptibility." (PMID 30467504, 2018). "Moreover, similar to ABC, expansion of human AMB associated with malaria is driven by IFNγ." (PMID 30387712, 2018). "Effective pathogen clearance during malaria hinges on the interplay between adaptive and innate immune responses, especially on T cells, B cells, antigen-presenting cells (APCs) and IFNγ response." (PMID 40746561, 2025). "Our data demonstrate that CXCR6+ CD127− Tr1 dominate the response to Pf infected red blood cell antigens, rapidly expand following malaria in vivo, and express IL-10 and IFNγ in vivo during both symptomatic malaria and asymptomatic parasitemia." (PMID 41000872, 2025). "The frequency of Tr1 cells that expressed IL-10, IFNγ, and PD-1 increased in both symptomatic malaria and asymptomatic parasitemia." (PMID 41000872, 2025). "These malaria-specific Tr1 cells seem to be the engine of IL-10 production in human disease and, in addition to IL-10, express large quantities of IFNγ, making them ideal for both reducing inflammation, via IL-10, and suppressing parasitemia." (PMID 40972121, 2025). "In contrast, NK cells from malaria‐naive North Americans were able to mount a significantly more robust IFNγ response than Ugandan NK cells when stimulated by cytokines, but were relatively worse at performing ADCC." (PMID 39493859, 2024). "The type I IFNs play a more complex role during malaria, such as promoting parasite clearance in the liver stage, suppressing IFNγ production of parasitic-specific CD4+ T cells, and promoting IL-10 producing Th1 cells." (PMID 38715061, 2024). "Through this analysis, we identified a population of activated, malaria-specific, interleukin-10 (IL-10) and interferon-gamma (IFNγ) expressing CD4+ T cells that were more common in primigravid versus multigravid women." (PMID 37634385, 2023). "An overlapping set of genes, HP, ICAM1, IFNG, TLR2, and TLR4 were found to contain SNPs statistically significantly associated with malaria in both maternal and child analyses." (PMID 37287037, 2023). "During malaria, there was a significant increase in the proportion of IFNγ+ Adaptive cells, consistent with an increased inflammatory and cytokine responsiveness of Adaptive NK cells during infection." (PMID 37968278, 2023). "The choice of cytokines and chemokines measured was based on their reported implication in severe malaria (i.e. IFNγ, TNF-α, IL6, IL-1β, RANTES, MIP-1, MCP-1, IP10)." (PMID 37350957, 2023). "Both Th1 and Tfh subsets contribute to protection against P. chabaudi infection, as in the human malaria, evidenced by the protective role of IFNγ and parasite-specific antibodies." (PMID 36993971, 2023). "The levels of nine cytokines measured in plasma revealed an increase of IL-6, IFNg, IL-22 and IL12p70 in children with symptomatic malaria compared to uninfected children." (PMID 36787308, 2023). "Transitional, IFNγ- Adaptive and PD1+ subsets were more transcriptionally active during malaria compared to CD56bright and IFNγ+ Adaptive subsets." (PMID 37968278, 2023). "Interferon gamma-induced protein 10 (CXCL10), a pro-inflammatory chemokine induced by multiple cytokines including IFNg, has been previously identified as a marker of malaria disease severity." (PMID 37465667, 2023). "T helper 1 (Th1) cells and other T helper subsets that express IFNγ are particularly important for malaria immunity." (PMID 37812650, 2023). "Previous studies have shown that strong inflammatory cytokines like TNF-a and IFNg appeared to be blocking Tfh differentiation in malaria-like infections." (PMID 37553348, 2023).
malaria (continued). "CD4 T cells play multiple essential roles in protection from malaria, including IFNγ mediated direct killing of parasites, and by providing help to B cells to produce antibodies required for protection." (PMID 37968278, 2023). "Primigravid women had higher percentages of malaria-specific, nnCD4+ T cells that co-express IL-10 and IFNγ compared with multigravid women." (PMID 37634385, 2023). "Within the CD4 T cell compartment, type 1 regulatory (Tr1) cells that co-produce IFNγ and IL-10 during malaria, dominate antigen-specific CD4 T cell responses in children in high endemic areas." (PMID 37968278, 2023). "PD1+, Transitional and IFNγ- Adaptive NK cells, had a large proportion of subset specific DEGs, suggesting unique NK cell subset specific activation pathways during malaria (subset specific DEGs 76%, 42% and 47% respectively)." (PMID 37968278, 2023). "Previous studies have implicated the activation of the type 1 interferon pathway in mitigating severe disease to mild malaria and interferon-gamma (IFNg) secretion with protection from clinical disease." (PMID 37465667, 2023). "We confirmed that malaria-specific IL-10/IFNγ co-producing cells also produce IL-21 using a flow cytometric assay." (PMID 37634385, 2023). "At baseline (C-1), γδ T and CD4+ T cells constituted the majority of cells producing IFNγ or TNF upon PfRBC stimulation among malaria pre-exposed Africans." (PMID 35922467, 2022). "Malaria-specific IFNγ+CD4+ T cells have been previously identified as a correlate of protection in the context of vaccination and natural infection." (PMID 35922467, 2022). "In this study, we have found that IFNγ-producing CD4+ T cells and DN γδ T cells co-producing IFNγ and TNF are associated with parasite control among lifelong malaria-exposed Africans." (PMID 35922467, 2022). "Several factors, like interferon gamma (IFN-γ), have been linked to severity of malaria in both mice and humans and a fundamental role in the etiology of experimental cerebral malaria (ECM) has also been attributed to T cells activated in the spleen." (PMID 34659202, 2021). "The cytokine profile over eight days of coinfection showed exacerbation in the cytokines MCP-1, IFNγ and TNFα in relation to the increase seen in animals with malaria." (PMID 33526848, 2021). "The three major types, namely, types 1, 2 and 3 interferons, are all involved in antiviral immunity with type 2, also called interferon gamma, additionally playing a major role in immunity against malaria." (PMID 35233116, 2021). "IFNγ plays a critical role in mediating protective immunity against both the pre-erythrocytic and blood-stage malaria parasites." (PMID 34899708, 2021). "These Vγ9Vδ2 T cells exhibit intrinsic reactivity to Plasmodium, with rapid degranulation and production of IFNγ and TNFα, even in malaria-naïve individuals." (PMID 33679787, 2021). "While children with asymptomatic malaria have increased IFNγ, TNF and IL-4 levels, IL-10 and CXCL10 were elevated in asymptomatically infected pregnant women." (PMID 33407502, 2021). "Inflammatory CD4+ T cells offer protection against malaria by producing IFNγ and TNFα such that P. falciparum infection or its replication is inhibited, thus preventing severe malaria." (PMID 34414129, 2021). "Following in utero malaria exposure, cord blood Vγ9Vδ2 T cells are preferentially activated, produce more IFNγ, and exhibit greater memory differentiation." (PMID 33679787, 2021). "Our data further demonstrated the involvement of IFNα and IFNγ genes in inflammation of liver injury during the erythrocytic stage of malaria." (PMID 34899708, 2021). "In malaria-naive volunteers the number of IFNγ secreting cells was low (<5) and only few subjects responded following vaccination." (PMID 33854065, 2021). "More importantly, various reports illustrated that IFNγ blockade alone only resulted in modest changes to Tfh cells in malaria." (PMID 36845571, 2021).
malaria (continued). "A similar strong IFNγ response was observed both in symptomatic malaria experienced adults and smear positive CHMI subjects using RNA-seq." (PMID 31900030, 2020). "In endemic settings, higher frequencies of Vδ2 cells, as well as higher percentages of Vδ2 T cells that produce IFNγ and TNF upon malaria antigen stimulation, have been associated with protection against parasitemia." (PMID 33085728, 2020). "Another recent study in a malaria endemic area found a subset of γδ T cells from uncomplicated malaria patients expressing Vδ9 T cell receptor that expanded and produced IFNγ and IL-10 when cultured in presence of P. falciparum antigen." (PMID 30809232, 2019). "They performed an IFNγ-specific ELISPOT after adenovirus vector-based immunization of malaria-naïve volunteers with CSP and AMA1." (PMID 30949162, 2019). "IFNγ signaling is critical for the development of hematopoietic progenitor subsets during acute experimental malaria, and given the important role for IL-12 in IFNγ production, reduced levels of IL-12 would likely impact hematopoiesis during malaria." (PMID 30809232, 2019). "In conclusion, pulmonary vascular damage in ALI is a consequence of IFNγ-activated lung endothelial cells capturing, processing, and cross-presenting malaria parasite antigen to specific CD8+T cells induced during infection." (PMID 31534124, 2019). "In pre-clinical vaccine studies for malaria, IFNγ producing CD8+ T-cells were induced and led to protection." (PMID 30037078, 2018). "This is because there is evidence from a malaria vaccine study that antigen-specific IFNγ producing CD4+ T-cells were reduced three to five-fold after freeze-thaw compared with fresh." (PMID 30037078, 2018). "Studies on human malaria revealed that the cytokine levels of TNFα, IFNγ and IL-12 in PBMCs infected with Plasmodium falciparum in vitro, remained elevated throughout the measurement period of 48 h after infection." (PMID 29495555, 2018). "In severe malaria in Malawian children, the inflammatory monocyte subset was expanded and activated with higher plasma levels of inflammatory cytokines (IFNα, IFNγ, TNF-α, IL-6) and chemokines (CCL2, CCL3, CCL4, CXCL10) than in convalescence." (PMID 30581439, 2018). "In the same way, NK and γδT lymphocytes produce IFNγ and TNFα in malaria patients, while polymorphisms within the natural killer cell complex modulate mouse cerebral malaria." (PMID 30533319, 2018). "Taken together, these data identify CD160 as signature of CD8+ T cell with high killing capacity and IFNγ production in the context of blood-stage malaria." (PMID 30483269, 2018). "Particularly concerning the stimulatory signaling required for optimal activation of CD4 T cells, which have a central role in protection against malaria by producing IFNγ and helping B cells to secrete antibodies." (PMID 28859168, 2017). "We have recently shown that in areas of high malaria transmission, inflammatory CD4 T cells producing IFNγ and TNFα dominate in immune adults, who rarely experience high-density infections or clinical malaria despite constant exposure to infection." (PMID 29097996, 2017). "CD4 T cells have a dual role in protection against blood-stage malaria by producing IFNγ and helping B cells to secrete antibodies." (PMID 28859168, 2017). "In conclusion, our data demonstrate that in the context of severe blood‐stage malaria, cDC1 promote the differentiation of parasite‐specific IFNγ+ TNF+ Th1 cells, to the expense of more regulatory IL‐10+ CD4 T cells." (PMID 28935714, 2017). "To evaluate the relevance of our findings in mice with respect to human vaccination, we analyzed the serum IFNγ data from a clinical trial of the candidate malaria vaccine RTS,S/AS01 (Trial NCT0007504912)." (PMID 29263880, 2017). "A Th1 cell population co-expressing IFNγ and IL-10 also plays a key role in protecting against severe malaria pathology." (PMID 28859168, 2017).
malaria (continued). "This study identified NRAMP1, IFNG, NOS2A, MBL, VDR, and certain TLR-associated genes as important for susceptibility to TB and malaria, and the list has been growing ever since." (PMID 28881572, 2017). "It was possible to genotype some samples of patients with malaria to the IFNG (+874A > T) gene rs2430561." (PMID 27435973, 2016). "We show that IL-10 produced by Tr1 cells protects against IFNγ-dependent, TNF-mediated tissue damage, but limited the control of parasites that cause malaria and VL." (PMID 26765224, 2016). "For example, increased survival of immunocompromised mice vaccinated with a combination of IFNγ plus malaria antigens was reported upon challenge with malaria." (PMID 27409587, 2016). "IFNγ not only has an important role in host resistance to Plasmodium infection but is also a key mediator of malaria pathogenesis." (PMID 27808089, 2016). "The objective of this study was to evaluate the frequency of -1031T>C, -308G>A and -238G>A TNFA, +874 A>T IFNG and -819C>T, and -592C>A IL10 gene polymorphisms and their association with malaria vivax and genomic ancestry." (PMID 27999453, 2016). "In severe malaria, there is an increased level of inflammatory cytokines, such as interferon gamma (IFN-γ, tumor necrosis factor alpha (TNF- α and interleukin (IL)-6." (PMID 26943639, 2016). "Since the IL22 gene is located in proximity to the IFNG gene which is highly important for malaria, it was taken into consideration for further investigations regarding the severity of malaria symptoms in a large case-control study." (PMID 27311945, 2016). "The expression of TLR4 by these populations makes them susceptible to the inflammatory effects of deleterious TLR4 activators TNFα and IFNγ, both of which are up-regulated in malaria." (PMID 26555697, 2015). "CD4+ T cell responses were measurable in nearly all children, with the majority of children having CD4+ T cells producing both IFNγ and IL-10 in response to malaria-infected red blood cells." (PMID 24415936, 2014). "Together these data indicate that the functional phenotype of the malaria-specific T cell response is heavily influenced by malaria exposure intensity, with IFNγ/IL10 co-producing CD4+ T cells dominating this response among highly exposed children." (PMID 24415936, 2014). "Prior studies employing cross-sectional or prospective cohort designs have found associations between cellular immune responses and protection from future malaria, including IFNγ responses to liver stage and/or merozoite stage malaria antigens." (PMID 24415936, 2014). "We quantified production of IFNγ, TNFα, and IL-10 (alone or in combination) by malaria-specific T cells, and analyzed the relationship of this response to past and future malaria incidence." (PMID 24415936, 2014). "CD4+ T cell IFNγ/IL-10 responses to the polyclonal mitogen PMA/Io have previously been shown to correlate with relative protection against severe malaria." (PMID 24415936, 2014). "The potential role that malaria-specific IFNγ/IL-10 co-producing CD4+ T cell cells play in mediating or inhibiting protective immunity in humans has not thus far been investigated." (PMID 24415936, 2014). "NK and NKT cells are important effectors of the innate immune response to malaria, directly recognizing Plasmodium-infected RBCs and malarial antigens, in addition to producing IFNγ in order to contain parasitaemia." (PMID 25242870, 2014). "We assessed transcription factor expression within the dominant population of malaria-specific IFNγ/IL-10 co-producing cells and found that these cells uniformly were TBet+ and FoxP3−." (PMID 24415936, 2014). "Course and outcome of both human and experimental blood-stage malaria critically depend on a finely tuned balance between both pro-inflammatory cytokines, as, e.g., IL-1β, TNFα, IFNγ, IL-6, and IL-12, and anti-inflammatory cytokines such as IL-4 and IL-10." (PMID 25408684, 2014).